FAM236A (family with sequence similarity 236 member A)
Synonyms: DMRTC1-AS1; LINC00684
Gene: Protein-coding gene on chromosome X (72,938,163 to 72,938,958, forward strand). Ensembl gene ENSG00000275520.
Homologues: Orthologues: mouse Fam236e (34% identical), rat Fam236d (34% identical), mouse Fam236f (33% identical). Paralogues in human: FAM236B (100% identical), FAM236C (91% identical), FAM236D (91% identical).